CD93 (CD93 molecule)
Diseases named in the same sentence as CD93 in open-access papers (continued):
Sharing a sentence is not in itself a finding about the gene and the disease.
nasopharyngeal carcinoma (6 papers, 2020 to 2025). A carcinoma arising from the nasopharyngeal epithelium. "CD93 expression upregulation was associated with poor clinical outcomes in glioblastoma and nasopharyngeal carcinoma (NPC)." (PMID 37660019, 2023). "Bao demonstrated CD93’s critical role in nasopharyngeal carcinoma progression and angiogenesis, showing that silencing CD93 in the CNE2 cell line significantly reduced proliferation." (PMID 40943530, 2025). "CD93 expression was upregulated in colorectal cancer and nasopharyngeal carcinoma." (PMID 37660019, 2023). "Bao and colleagues investigated the role of CD93 in regulating nasopharyngeal carcinoma (NPC) progression and found an increased CD93 expression in NPC." (PMID 37443812, 2023). "Previous explorations have shown that CD93 is significantly upregulated and plays an important role in tumor vasculatures of renal cell carcinomas, pancreatic adenocarcinoma, nasopharyngeal carcinoma and colon cancer, which made it a probable antiangiogenic target for these cancers." (PMID 36006582, 2022).
psoriasis (6 papers, 2022 to 2025). An autoimmune condition characterized by red, well-delineated plaques with silvery scales that are usually on the extensor surfaces and scalp. "CD93 single-nucleotide polymorphisms (SNPs) and mutations have been found to be associated with autoimmune diseases (AIDs), such as psoriasis and AMD." (PMID 40904461, 2025). "The CD93 gene has been implicated in the pathogenesis of psoriasis, a chronic inflammatory skin condition." (PMID 40943530, 2025). "The studies discussed in this section showed that the C/C genotype of the SNP rs2749817 of CD93 was associated with psoriasis onset, while the T/T genotype of rs2749817 was commonly found in patients with stage IV CRC." (PMID 37443812, 2023). "Thus, the increased CD93 expression of psoriatic skin may be associated with the rs2749817 polymorphism, suggesting an important role of CD93 in psoriasis disease pathogenesis." (PMID 37443812, 2023). "The involvement of the CD93-mediated signaling pathway in keratinocyte dysfunction highlights the importance of this gene in the pathophysiology of psoriasis." (PMID 40943530, 2025). "Four genes (SELP, CD93, VAV1, and IL2RG) were identified as the most reliable diagnostic indicators for psoriasis." (PMID 40539722, 2025). "Shehata and colleagues investigated the role of CD93 in modulating inflammation in this pathology and found that CD93 expression was increased in both endothelial and inflammatory cells of patients affected by psoriasis." (PMID 37443812, 2023). "Notably, the expression of CD93 has an essential role in the pathogenesis of psoriasis, cardiovascular, and cerebrovascular diseases." (PMID 36761750, 2023). "They found increased CD93 immunofluorescence in the dermal ECs of lesional skin and elevated CD93 gene expression in psoriasis patients compared to controls, irrespective of skin damage." (PMID 40943530, 2025). "Another study found that the expression of the CD93 gene was increased in lesioned and non-lesioned skin of patients with psoriasis." (PMID 37443812, 2023).
lung carcinoma (5 papers, 2022 to 2025). "Notably, high CD93 scores in the vasculature of lung cancer metastasis were associated with higher MMRN2 and fibronectin scores in the same tumor tissue." (PMID 38441970, 2024). "Analyses of squamous cell carcinoma biopsies from lung cancer patients and ductal cancer cells from postmenopausal breast cancer patients revealed downregulated CD93 expression compared to controls." (PMID 40943530, 2025). "We then evaluated the relationship between CD93 level in pMCs and T-cell responses in lung cancer patients." (PMID 38250037, 2024). "Since MCs of lung cancer patients were unavailable, we measured miR-5193 level in EVs instead of directly detecting CD93 level in pMCs to assess that." (PMID 38250037, 2024). "Additionally, anti-CD93 can overcome lung tumor resistance to anti-PD-1 therapy, offering a promising strategy for lung cancer treatment." (PMID 40943530, 2025). "In addition, we found that miR-5193 (human miR-5110 homolog) was enriched in TT-EVs from lung cancer patients, and TT-EVs significantly inhibited CD93 expression in NCI-H2452 cells." (PMID 38250037, 2024). "Thus, CD93 in pMCs is also probably involved in the regulation of T-cell responses in lung cancer patients by promoting CCL21-mediated DC recruitment." (PMID 38250037, 2024). "These suggest that IL-17D might regulates lung cancer cells producing cytokines through CD93 on lung cancer cells, which indirectly leads to TAM infiltration." (PMID 35939336, 2022). "Furthermore, lung cancer patients with higher serum EV-derived miR-5193 (human miR-5110 homolog) are more sensitive to anti-PD-1 therapy, while patients with higher serum C1q are less sensitive, consistent with their regulatory functions on CD93." (PMID 38250037, 2024). "More importantly, as a negative or positive regulator of CD93, high sEV-derived miRNA-5193 or C1qA were associated with favorable or unfavorable progression-free survival (PFS) after anti-PD-1 therapy in lung cancer patients." (PMID 38250037, 2024).
pancreatic cancer (5 papers, 2021 to 2025). "In this study, Hu-PBMC mice bearing orthotopic pancreatic tumors were used to evaluate the therapeutic efficacy of our allogeneic DC treatment platform utilizing a lentiviral vector carrying CD93, CD40L, and CXCL13 with tumor-specific antigen pulsing." (PMID 40733726, 2025). "In this paper, we present a strategy for engineering CD34+ cells to derive mDCs, overexpressing CD93, CD40L, and CXCL13, followed by antigen pulsing for enhanced targeting of pancreatic tumors." (PMID 40733726, 2025). "However, according to the IHC results from the HPA, except for liver, stomach, and pancreatic cancer, the CD93 protein was negative in most tumors." (PMID 35265666, 2021).
autoimmune disease (4 papers, 2013 to 2025). A disorder resulting from loss of function or tissue destruction of an organ or multiple organs, arising from humoral or cellular immune responses of the individual to their own tissue constituents. "Autoimmune diseases are also closely associated with inflammatory responses, as evidenced by the significant correlation between CD93 expression and conditions like systemic lupus erythematosus and systemic sclerosis." (PMID 40943530, 2025). "In the context of clinical diseases, CD93 has been implicated in a range of pathological conditions, including inflammation, cardiovascular diseases, autoimmune disorders, and various cancers." (PMID 40943530, 2025). "Aberrant CD93 expression has been observed in various pathological conditions, including inflammation, cardiovascular diseases, autoimmune disorders, and cancer." (PMID 40943530, 2025).
chronic myeloid leukemia (4 papers, 2020 to 2023). "CD93 signaling blocking with metoclopramide significantly impaired the stemness and proliferation of chronic myeloid leukemia stem cells." (PMID 36006582, 2022).
gastric cancer (4 papers, 2022 to 2025). A primary or metastatic malignant neoplasm involving the stomach. "From 2023 to 2025, multiple research teams consistently identified CD93 as a gene significantly associated with gastric cancer (GC)." (PMID 40943530, 2025). "Next, we determined that the CD93+ cell number and the OD values of CD93+ cells in different regions of stomach cancer were significantly different (p = 0.0292 and p = 0.0400, respectively)." (PMID 36761750, 2023). "To verify the prognostic significance of CD93 in stomach cancer, we downloaded transcriptome and related clinical data from GEO datasets (GSE26253, n = 432)." (PMID 36761750, 2023). "Subsequently, digital image analysis results by QuPath revealed that the properties of CD93+ cells were statistically significant in different regions of stomach cancer and normal stomach tissue." (PMID 36761750, 2023). "Moreover, we checked for CD93 expression difference between stomach cancer and normal stomach tissue by using the digital image analysis (DIA) software QuPath." (PMID 36761750, 2023). "Furthermore, we recognized the CD93+ and CD93- cells in different regions of stomach cancer and normal stomach tissue." (PMID 36761750, 2023). "We lack further experiments to verify the precise molecular function of CD93 in stomach cancer." (PMID 36761750, 2023). "In addition, we identified three key mRNAs (CD93, COL3A1 and COL4A1) associated with gastric cancer peritoneal metastasis through WGCNA analysis and clinical specimen validation." (PMID 36690975, 2023). "The innovative combination validated the expression of CD93 in stomach cancer." (PMID 36761750, 2023). "CD93 was linked to poor prognosis of STAD, the abundance of multiple immune cell infiltration levels, and neutrophil extracellular traps (NETs), which are crucial for cancer occurrence and metastasis, and could also serve as a prognostic indicator for gastric cancer patients." (PMID 40943530, 2025). "Intriguingly, lnc-TRIM28-14 was positively correlated with the expression levels of CD93 and COL4A1 in gastric cancer peritoneal metastasis, suggesting a regulatory relationship between them." (PMID 36690975, 2023). "In this study, we performed whole-transcriptome sequencing on tissue samples of gastric cancer peritoneal metastasis, and identified GCPM-related lncRNAs (lnc-RFNG-1 and lnc-TRIM28-14) and mRNAs (CD93, COL3A1, and COL4A1)." (PMID 36690975, 2023). "Based on the results of tissue segmentation and cell recognition, we observed that CD93+ cell was overexpressed in stomach cancer compared with normal stomach tissue." (PMID 36761750, 2023). "Moreover, there was a positive correlation between lnc-TRIM28-14 and the expression of CD93 and COL4A1 in gastric cancer peritoneal metastasis, suggesting a regulatory relationship between them." (PMID 36690975, 2023).
peritonitis (4 papers, 2019 to 2025). Inflammation of the peritoneum (tissue that lines the abdominal wall and covers most of the organs in the abdomen). "Greenlee-Wacker and colleagues investigated the role of CD93 in inflammation and found that CD93−/− mice showed an increase in leukocyte infiltration during thioglycolate-induced peritonitis due to an impaired vascular integrity in these mice." (PMID 37443812, 2023). "For mice models with peritonitis, CD93 was verified to adjust the recruiting, migrating and adhesion processes of leukocytes." (PMID 36006582, 2022).
stomach adenocarcinoma (4 papers, 2023 to 2025). "Accordingly, two bioinformatic studies have suggested the overexpression of CD93 in gastric adenocarcinoma, demonstrating strong associations between CD93 expression and tumor microenvironment." (PMID 39190192, 2024). "Meanwhile, Zhu and colleagues revealed that CD93 was associated with immune subtypes characterized by a distinct tumor immune microenvironment and patient prognosis in stomach adenocarcinoma (STAD)." (PMID 36761750, 2023). "Herein, we aimed to investigate the expression and clinicopathological significance of CD93 in gastric adenocarcinoma." (PMID 39190192, 2024). "Our study revealed a significantly higher CD93 expression in gastric adenocarcinoma when compared with adjacent normal gastric tissues, and demonstrated its predominant expression on vascular endothelial cells." (PMID 39190192, 2024). "More importantly, multivariate analysis underscored CD93 expression as an independent prognostic predictor for gastric adenocarcinoma patients." (PMID 39190192, 2024). "The immunohistochemistry assay revealed a highly variable CD93 expression among patients with gastric adenocarcinoma, consistently demonstrating higher intratumor expression than in adjacent normal tissues." (PMID 39190192, 2024). "The gene expression of CD93 gastric adenocarcinoma was assessed using The Cancer Genome Atlas (TCGA) dataset." (PMID 39190192, 2024). "Using the TCGA dataset, we observed a significantly elevated CD93 gene expression in gastric adenocarcinoma compared to normal gastric tissues." (PMID 39190192, 2024). "Taken together, our data showed that CD93 was overexpressed in patients with gastric adenocarcinoma and was mainly expressed on CD31+ vascular endothelial cells." (PMID 39190192, 2024). "To validate the findings from the public database, we further performed an immunohistochemistry assay to investigate the expression of CD93 in gastric adenocarcinoma." (PMID 39190192, 2024). "In this study, we observed significantly higher expression of CD93 in gastric adenocarcinoma when compared to that of adjacent normal tissues, with CD93 primarily expressed on the membrane of vascular endothelial cells." (PMID 39190192, 2024). "Our findings also highlighted the clinicopathological significance of CD93 in gastric adenocarcinoma, shedding light on a potential therapeutic target." (PMID 39190192, 2024). "To address this, we first assessed the expression and clinical correlation of CD93 in gastric adenocarcinoma using data from The Cancer Genome Atlas Program (TCGA)." (PMID 39190192, 2024). "In conclusion, our study indicated a significantly higher expression of CD93 in gastric adenocarcinoma and found that the level of CD93 expression was strongly associated with clinical severity and prognosis." (PMID 39190192, 2024). "Cox proportional hazards regression suggested CD93 expression was an independent predictor for the prognosis of patients with gastric adenocarcinoma." (PMID 39190192, 2024). "Next, we involved 404 patients with gastric adenocarcinoma to investigate the expression of CD93 at the protein level and evaluated its clinical pathological role." (PMID 39190192, 2024). "As a result, we found that the gene expression of CD93 in gastric adenocarcinoma was significantly higher than that in normal tissues." (PMID 39190192, 2024). "Furthermore, we not only characterized a more severe clinical phenotype in patients with higher CD93 expression but also identified CD93 as an independent predictor of the prognosis in patients with gastric adenocarcinoma." (PMID 39190192, 2024). "Accordingly, using both the public RNA-seq dataset and our observations from immunohistochemistry, we determined that the expression of CD93 was significantly upregulated in gastric adenocarcinoma tissues and was mainly expressed on the membrane of CD31+ vascular endothelial cells." (PMID 39190192, 2024).
stomach adenocarcinoma (continued). "We finally performed Cox regression to determine whether CD93 expression was a predictor of the prognosis of patients with gastric adenocarcinoma." (PMID 39190192, 2024). "Notably, although CD93 expression was highly variable among these patients with gastric adenocarcinoma, we observed that the expression of CD93 in tumors was significantly higher than that in adjacent normal tissues." (PMID 39190192, 2024). "We then analyzed CD93 expression in 404 cases of gastric adenocarcinoma using immunohistochemistry." (PMID 39190192, 2024). "We first estimated the gene expression of CD93 in gastric adenocarcinoma using data from TCGA." (PMID 39190192, 2024). "CD93, as a type I transmembrane glycoprotein, was correlated with tumor-associated angiogenesis; however, how CD93 correlates with immunotherapy in stomach adenocarcinoma (STAD) remains unclear." (PMID 36761750, 2023). "Additionally, gastric adenocarcinoma patients with higher expression of CD93 demonstrated deeper invasion, higher proportion of lymph node metastasis, higher possibility of developing tumor thrombus, resulting in advanced tumor stage." (PMID 39190192, 2024).
systemic sclerosis (4 papers, 2020 to 2025). A chronic disorder, possibly autoimmune, marked by excessive production of collagen which results in hardening and thickening of body tissues. "CD93 was also involved in important inflammatory-associated diseases such as systemic sclerosis and neuroinflammation." (PMID 37443812, 2023). "Accordingly, CD93 is involved in modulating important inflammatory-associated diseases including systemic sclerosis and neuroinflammation." (PMID 37443812, 2023).
colorectal cancer (3 papers, 2015 to 2023). A primary or metastatic malignant neoplasm that affects the colon or rectum. "We evaluated the expression of CD93 and the association with two single nucleotide polymorphisms (SNPs), rs2749812 and rs2749817, as possible biomarkers in colorectal cancer (CRC)." (PMID 26008729, 2015). "In a recent example, elevated levels of CD93 expression were detected on human colorectal carcinoma sections." (PMID 31287944, 2019). "Interestingly, this study also examined soluble levels of CD93 within patient plasma and found a 30% reduction in colorectal carcinoma patients compared with healthy controls." (PMID 31287944, 2019).
lymph node metastasis (3 papers, 2019 to 2024). "Accordingly, higher CD93 expression was associated with deeper invasion and a higher possibility of lymph node metastasis and developing tumor thrombus." (PMID 39190192, 2024). "The neoantigen of CD93 only occurs in breast cancer with lymph node metastasis and indicates a close relationship between angiogenesis and lymph node metastasis." (PMID 30670769, 2019). "In contrast, the gene expression of CD93 was independent of the condition of lymph node metastasis or Helicobacter pylori infection." (PMID 39190192, 2024). "The results suggest that the expression of ECM2, PCDH12, EPAS1, CD93, DLL4, and ARHGEF15 are significantly different in age, N (lymph node metastasis status), and whether radiotherapy is received or not." (PMID 35953532, 2022).
lymphoma (3 papers, 2013 to 2016). A malignant (clonal) proliferation of B- lymphocytes or T- lymphocytes which involves the lymph nodes, bone marrow and/or extranodal sites. "Of the mice injected with selected B cell populations, 40% of B220+ and CD19+ injected mice developed lymphoma, but only 20% of those injected with CD93+ cells developed lymphoma and all of those injected with CD117+ cells or CD3+ control cells remained healthy." (PMID 23985023, 2013). "We found that all of the lymphoma samples consistently expressed B220, CD24, CD38, CD43, CD93, and CD138." (PMID 26740101, 2016). "We found that, with one exception (mouse 353), all of the lymphoma cells stained positive for CD19, CD45R/B220 and high AA4.1 (CD93) expression and negative for CD5 and CD3, indicating that they are early stage B-cells, either surface IgM− or IgM+, in both Mtap+/+ and MtaplacZ/+ mice." (PMID 23840755, 2013).
measles (3 papers, 2016 to 2024). A highly contagious viral infection caused by the measles virus. "Interestingly, we previously identified IL-24 (IL24) along with CD93 as markers of differential MV-specific transcriptional response (in PBMCs) in 15 high vs. 15 low antibody responders to measles vaccination." (PMID 38633249, 2024). "This is further corroborated by a recent study looking at measles titers of vaccinated school children in which the most highly expressed genes in high responder groups were CD93, IL-6, and CXCL12- implicating CD93 involvement in the generation of long-lived antibody responses in humans." (PMID 31130955, 2019).
Obesity (3 papers, 2011 to 2024). Accumulation of substantial excess body fat. "This was demonstrated for the angiogenic marker CD93, which has a pathogenic role both in the context of obesity and cardiovascular disease, as well as in preeclampsia, emphasizing the relevance of these markers in broader pathological contexts." (PMID 39858399, 2024). "Further research is needed to better understand the complex interplay between CD93 and obesity and develop novel treatments to fight this highly prevalent and morbid clinical condition." (PMID 37371490, 2023).
type 2 diabetes (3 papers, 2020 to 2023). "In the longitudinal genome-wide study by Chan and colleagues on 15,346 women of different ethnicities, CD93 ranked among the top 10 key driver genes commonly shared between CVD and type 2 diabetes." (PMID 37371490, 2023).